INSL3 (insulin like 3)
Diseases named in the same sentence as INSL3 in open-access papers (continued):
Sharing a sentence is not in itself a finding about the gene and the disease.
Cachexia (4 papers, 2021 to 2026). Severe weight loss, wasting of muscle, loss of appetite, and general debility related to a chronic disease. "We end this review with a discussion of three recently identified central mediators of cachexia, including GDF15, LCN2 and INSL3, all peripherally derived molecules that bind to their cognate receptors in the brain to drive cachexia symptoms." (PMID 34439145, 2021). "Although not shown experimentally, the authors suggest that inhibition of Dilp3/INSL3 did not improve cachexia-associated lean and fat mass wasting despite the observed improvement in food intake." (PMID 34439145, 2021). "Indeed, just the past 2 years of research identified GDF15, Lipocalin 2 (LCN2) and insulin-like 3 peptide (INSL3) as novel peripherally derived factors that activate CNS circuitry to drive cachexia symptoms." (PMID 34439145, 2021). "However, it remains unclear if LCN2 or INSL3 influence other CNS mechanisms of cachexia beyond nutrition at this time." (PMID 34439145, 2021). "Therefore, it will be interesting to analyze whether known tumor-derived factors, such as INSL3 and IGFBP, are also involved in chemotherapy-induced cachexia." (PMID 35388147, 2022). "Therefore, it appears as though Dilp3/INSL3 signaling in the brain specifically improves feeding behaviors without sparing lean or fat mass wasting during cancer cachexia." (PMID 34439145, 2021).
hypogonadotropic hypogonadism (4 papers, 2015 to 2023). Abnormal ovarian or testicular function due to insufficient hormonal stimulation from the hypothalamic-pituitary axis. "Further argument supporting a stimulatory effect of hCG on INSL3 in humans comes from the observation that patients with hypogonadotropic hypogonadism have an INSL3 production which is dependent on the differentiating effect of LH/hCG on Leydig cells." (PMID 25706302, 2015). "All three hypogonadal categories had significantly reduced INSL3 concentrations compared to the eugonadal subjects, though these were mostly not different from one another, except that primary hypogonadism appeared to be reduced compared to secondary hypogonadism." (PMID 36425465, 2022).
Leydig cell tumor (4 papers, 2021 to 2023). A sex cord-stromal tumor occurring in the testis and rarely in the ovary. "Other reports highlight the potential role of INSL3 as a marker of human testicular Leydig cell tumors." (PMID 35178089, 2022). "As a hormone produced by Leydig cells, INSL3 was also deemed to distinguish Leydig cell hyperplasia and Leydig cell tumor with high accuracy." (PMID 34233048, 2021). "In accordance with this, our previous immunohistochemical study revealed that INSL3 was expressed in normal human Leydig cells and Leydig cell tumors, but not in TART." (PMID 37256668, 2023).
pancreatic cancer (4 papers, 2021 to 2025). "In pancreatic cancer patients, a higher serum level of INSL3 was associated with increased anorexia." (PMID 35178089, 2022). "Serum INSL3 levels were found significantly increased in patients with pancreatic cancer cachexia and serum INSL3 levels were negatively correlated to calorie intake in such patients." (PMID 36078078, 2022). "We cannot, therefore, support the notion of INSL3 as a novel pancreatic cancer biomarker." (PMID 40937417, 2025).
Anorexia (3 papers, 2022). Lack of desire to eat (loss of appetite). "We recently reported that a new type of cytokine, Dilp8/INSL3, induces anorexia in cancer patients." (PMID 35388147, 2022). "The peripheral injection of INSL3 in LLC tumor-bearing mice initially showed no changes in food intake, but these mice ultimately developed anorexia." (PMID 35388147, 2022).
diabetes (3 papers, 2021 to 2022). "The present study examined the differences in INSL3 expression in serum of DN, type 2 diabetes mellitus (T2DM), and healthy populations." (PMID 34233048, 2021). "We detected that the expression of INSL3 notably increased in both serum sample and high‐glucose‐treated SV40‐MES‐13 cells compared with samples from type 2 diabetic mellitus patients, healthy controls, and normal‐glucose‐treated SV40‐MES‐13." (PMID 34233048, 2021).
polycystic ovary syndrome (3 papers, 2019 to 2023). A disorder that manifests as multiple cysts on the ovaries. "It was claimed that INSL3 is a valuable indicator in women with polycystic ovary syndrome and premature ovarian failure." (PMID 34233048, 2021). "INSL3 expression is consequently increased in polycystic ovary syndrome (PCOS) and decreased in females with POF, which might be a valuable biomarker for POF patients." (PMID 37332766, 2023).
anorchia (2 papers, 2011 to 2016). "We evaluated the clinical and biological presentation, and family histories of 26 boys with anorchia, and sequenced their SRY, NR5A1, INSL3, MAMLD1 genes and the T222P variant for LGR8." (PMID 21853106, 2011). "All patients with anorchia were sequenced for SRY, NR5A1, INSL3, MAMLD1 and the T222P variant of LGR8 and no pathogenic mutations were identified." (PMID 27899089, 2016).
hyperandrogenism (2 papers, 2016 to 2022). Excessive secretion of androgens from the adrenal glands or gonads. "Among women with PCOS, the highest level of INSL3 is described as functional ovarian hyperandrogenism, which is characterized by more severe hyperandrogenism and insulin resistance." (PMID 36303231, 2022). "In this study, we aimed to investigate the diagnostic value of AMH, INSL3, INH-A, and INH-B in adolescents with PCOS and also to explore the association between these hormones and the clinical/laboratory findings related with hyperandrogenism." (PMID 27125339, 2016).
Hypertension (2 papers, 2022 to 2024). The presence of chronic increased pressure in the systemic arterial system. "Elevated INSL3 also associates with hypertension and cardiovascular disease." (PMID 36425465, 2022). "Significantly, INSL3 is still seen to be associated with both hypertension and cardiovascular disease, though to no other morbidity." (PMID 36425465, 2022). "This study shows that adrenal gland gene expression of RXFP2 is increased in men with hypertension and the RXFP2 natural ligand, INSL3, increases adrenal steroidogenesis and corticosteroid secretion in human adrenal cells." (PMID 38851835, 2024).
preeclampsia (2 papers, 2011 to 2018). Preeclampsia is a hypertensive disorder of pregnancy that is characterized by new-onset hypertension with proteinuria presenting after 20 weeks of gestation, and depending on mild or severe forms may initially present with severe headache, visual disturbances, and hyperreflexia. "A similar significant increase in INSL3 expression was also noted in the previous, smaller study of United States amniotic fluid samples in relation to preeclampsia." (PMID 29740335, 2018).
primary hypogonadism (2 papers, 2018 to 2022). "Since primary hypogonadism is more common amongst older men, the results were re-analyzed, correcting for age, by plotting the interpolated values from INSL3 against age regressions within each category, normalized to an individual of 65 years." (PMID 36425465, 2022). "In central or primary hypogonadism, low testosterone and/or INSL3 are responsible for the testicular maldescent." (PMID 29922225, 2018). "Consequently, circulating INSL3 is a measure of testicular steroidogenic capacity and hence also a sensitive biomarker of primary hypogonadism." (PMID 36425465, 2022).
adenoma (1 paper, 2022). A neoplasm arising from the epithelium. "Impaired INSL3 expression has previously been reported in human testicular samples with Leydig cell hyperplasia and adenomas." (PMID 35158595, 2022).
amenorrhea (1 paper, 2019). The absence of menses in a woman who has achieved reproductive age. "INSL3 and AMH levels are increased in patients of amenorrhea and oligomenorrhea, reflecting a dysfunction of the thecal and granulosa cells in PCOS." (PMID 31983920, 2019).
Atrophy (1 paper, 2018). Any weakening or degeneration, especially through lack of use. "The possible role of INSL3/RXFP2 pathway on skeletal muscle was assessed in vivo through the application of an atrophy model on Rxfp2−/− mice." (PMID 30323788, 2018).
central precocious puberty (1 paper, 2024). "The aim of the study is to quantify INSL3 by LC-MS/MS in sera from normal girls during pubertal transition, and during gonadal suppression by GnRH agonist therapy in girls with central precocious puberty (CPP)." (PMID 39010900, 2024). "We measure serum INSL3 in healthy peripubertal girls as well as in girls with central precocious puberty (CPP) before, during and after GnRHa treatment." (PMID 39010900, 2024). "In the girls with central precocious puberty (CPP) we also observed a significant decrease in serum INSL3 during treatment with GnRH agonist followed by a marked increase after end of treatment." (PMID 39010900, 2024). "Future studies in a larger group of CPP individuals may reveal if serum INSL3 may contribute to the panel of biomarkers for pubertal onset which in combination may contribute to distinguish between premature thelarche and central precocious puberty." (PMID 39010900, 2024).
chickenpox (1 paper, 2025). A contagious childhood disorder caused by the varicella zoster virus. "Analysis of data from the ALSPAC cohort implies that of various parameters assessed, only childhood and adolescent BMI as well as early infectious disease, in particular chickenpox, have any influence on young adult INSL3 concentration, respectively reducing circulating levels each by 10%-20%." (PMID 40605237, 2025). "Particularly, chickenpox in infancy had a marked and significant negative association with INSL3 (reduced by 10%-14%) at both 17 and 24 years." (PMID 40605237, 2025).
Delayed puberty (1 paper, 2022). Passing the age when puberty normally occurs with no physical or hormonal signs of the onset of puberty. "INB performed better than INSL3 in differentiating CHH in boys with delayed puberty (auROC 98.5%, 95.9-100%), than in adult men (auROC 93.9%, 87.2-100%)." (PMID 36523592, 2022). "However, INSL3 more accurately differentiated CHH in adult men than in boys with delayed puberty (auROC with 95% CI in adult men: 100%, 100-100%; boys with delayed puberty: 86.7%, 77.7-95.7%)." (PMID 36523592, 2022).
depression (1 paper, 2022). "Only cFT showed any relationship with the index of depression (BDI), and only INSL3 and cFT predicted a relationship with overall sexual function (osf) and reduced bone mineral density (BMD)." (PMID 36425465, 2022).
diabetic nephropathy (1 paper, 2021). "This present study aimed to explore the underlying mechanisms of INSL3 in diabetic nephropathy (DN)." (PMID 34233048, 2021).
gastric cancer (1 paper, 2012). A primary or metastatic malignant neoplasm involving the stomach. "Of the NHL-related gene panel, one SNP in nine genes remained marginally significant (FDR-BH p-value = 0.09); INSL3 rs10421916 was associated with a significantly decreased for gastric cancer (OR [95% CI] = 0.6 [0.3–0.97])." (PMID 23028900, 2012). "In conclusion, our findings suggest DEFA6, DEFB1, and INSL3 genetic variants are susceptibility factors for the development of gastric cancer." (PMID 23028900, 2012). "INSL3 rs10421916 and rs11088680 had both a 0.8-fold decreased OR for gastric cancer (95% CIs = 0.7–0.97; and 0.7–0.9, respectively)." (PMID 23028900, 2012). "In the Replication genotyping phase with more case-control sets and in the meta- and pooled analyses, DEFA6, DEFB1, and INSL3 were still significantly associated with gastric cancer risk without heterogeneity across the phases." (PMID 23028900, 2012).
gonadal dysgenesis (1 paper, 2024). A congenital disorder characterized by the presence of extremely hypoplastic gonads preventing the development of secondary sex characteristics. "Hormonal evaluations in prepubertal boys may also help to identify the underlying causes of testicular descent disorders, such as gonadal dysgenesis, disorders of androgen synthesis, androgen insensitivity, or disruptions in AMH and INSL3 production or action." (PMID 39797156, 2024).
hypovitaminosis D (1 paper, 2026). "Reduced BMD values have been attributed to testosterone deficiency, hypovitaminosis D, lower concentration of insulin‐like factor 3 (INSL‐3), and alterations in body composition, which are frequently observed in these subjects." (PMID 40191911, 2026). "Therefore, in addition to testosterone, other factors may play a role in the skeletal fragility and in the fracture risk, such as hypovitaminosis D, reduced INSL‐3 levels, low estrogen levels, altered AR function and sensitivity and reduced lean mass." (PMID 40191911, 2026).
Inguinal hernia (1 paper, 2006). Protrusion of the contents of the abdominal cavity through the inguinal canal. "From studies using transgenic knockout mice and humans, INSL3 is believed to be the primary testicular hormone inducing gubernacular development, and has been associated with occurrences of inguinal hernia in female mice." (PMID 16672048, 2006).
ovarian diseases (1 paper, 2025). "These novel findings could challenge previous research on INSL3 and may serve as a new target marker for the treatment of human ovarian diseases and for enhancing reproductive rates in ruminants." (PMID 41516279, 2025). "Future studies should utilize in vivo models to systematically analyze the INSL3-STAR regulatory axis, providing a theoretical basis for the targeted treatment of ovarian diseases and the enhancement of reproductive efficiency in livestock and poultry." (PMID 41516279, 2025).
sexual dysfunction (1 paper, 2022). Disturbances in sexual desire and the psychophysiologic changes that characterize the sexual response cycle and cause marked distress and interpersonal difficulty. "Whether INSL3 is also predictive of sexual dysfunction is not known and hence correlation analysis was applied." (PMID 36425465, 2022).
tuberculosis (1 paper, 2021). A chronic, recurrent infection caused by the bacterium Mycobacterium tuberculosis. "The decision tree identified INSL3 and RAB20 (Decision-tree genes) as the optimal gene set to classify tuberculosis status among patients from both sites." (PMID 33692804, 2021).
varicocele (1 paper, 2024). A condition characterized by the dilated tortuous veins of the spermatic cord with a marked left-sided predominance. "However, the authors found a strong positive correlation between INSL-3 and semen quality, and the different severity of the disease in patients with varicocele was associated with serum INSL-3 levels." (PMID 38330789, 2024). "In particular, serum INSL-3 can well distinguish between Grade I and Grade II patients, which helps to understand the potential pathophysiological mechanism of varicocele and is expected to become a potential biomarker for early clinical intervention." (PMID 38330789, 2024). "In this study, serum InhB and INSL-3 levels were combined with basic semen parameters to evaluate the degree of varicocele." (PMID 38330789, 2024). "Semen parameters and the combination of serum InhB and INSL-3 levels in patients with varicocele are closely related to the severity of the disease." (PMID 38330789, 2024). "The authors found that the serum InhB and INSL-3 in patients with varicocele were higher, and the levels decreased with the severity of the disease." (PMID 38330789, 2024). "Serum INSL-3 in patients with varicocele decreased with the severity of the disease." (PMID 38330789, 2024). "•Serum INSL-3 in patients with varicocele decreases with the severity of the disease." (PMID 38330789, 2024). "Semen volume, concentration, total sperm, normal sperm morphology, and serum InhB and INSL-3 levels could distinguish the degree of varicocele." (PMID 38330789, 2024). "It is speculated that INSL-3 and testosterone production are independent under pathological conditions, and INSL-3 and semen quality can well evaluate the disease degree of patients with varicocele." (PMID 38330789, 2024). "•Serum InhB and INSL-3 levels could distinguish the degree of varicocele." (PMID 38330789, 2024). "Based on this, the authors boldly assumed that InhB and INSL-3 were related to spermatogenesis and semen quality, and semen parameters were related to the ability of serum InhB and INSL-3 levels to distinguish varicocele." (PMID 38330789, 2024). "Further, serum InhB and INSL-3 were correlated with the degree of varicoceles, and serum InhB and INSL-3 decreased with the severity of the disease, especially serum INSL-3." (PMID 38330789, 2024).
Zinc deficiency (1 paper, 2024). A deficiency of the essential metal Zinc; an essential cofactor for many enzymes. "Liver levels of INSL3, INSL7, and MDA were significantly different in zinc-deficiency diet group than zinc-supplemented group." (PMID 38407794, 2024).
cancer (12 papers, 2017 to 2025). A tumor composed of atypical neoplastic, often pleomorphic cells that invade other tissues. "Of the five hormone parameters assessed, only increased LH had any predictive value in regard to reduced physical activity and, like INSL3, also showed a significant association with ever having had cancer." (PMID 36425465, 2022). "Lastly, the discovery of RXFP2’s unique role in cancer, mediated by its interaction with INSL3, opens new avenues for targeted cancer therapies." (PMID 39000413, 2024). "Nevertheless, INSL3 regulates skeletal muscle physiology through the Akt/mTor/S6 pathway, playing a role in cancer cachexia." (PMID 36078078, 2022). "The study showed that the secretion of INSL3 into cell culture medium and serum INSL3 levels are increased in a mouse cancer model and human cancer patients, respectively." (PMID 35388147, 2022). "Future studies are needed to investigate the potential effects of the Dilp3/INSL3–Lgr3/Lgr8 pathway in cancer cachexia." (PMID 36078078, 2022). "Future studies are warranted in order to investigate potential nutrition-independent effects of the Dilp3/INSL3–Lgr3/Lgr8 axis during cancer cachexia." (PMID 34439145, 2021). "Given these hypothalamic regions play diverse roles in whole-body metabolism, including regulation of the HPA axis and autonomic signaling, it is plausible that the proposed Dilp3/INSL3–Lgr3/Lgr8 mediates other components of cancer cachexia." (PMID 34439145, 2021). "Application of recombinant INSL3 to reproductive, andrological, ophthalmic, bone and cancer fields helps to alleviate adverse symptoms in these areas." (PMID 29229959, 2017). "Furthermore, Yeom and colleagues, using mouse cancer models as well as findings from human cancer patients, postulated that INSL3 was produced by tumors, such as PDAC, and was responsible for inducing cachexia in these patients." (PMID 40937417, 2025). "The tumor-promoting effect of INSL3 in cancer has also been widely addressed." (PMID 35178089, 2022). "We demonstrated that the regulation of INSL3 in cancer anorexia is conserved in mice." (PMID 35388147, 2022). "Using one of these assays, we have reassessed here the role of INSL3 as a PDAC biomarker and its possible role in cancer cachexia." (PMID 40937417, 2025). "It seems likely that Dilp3/INSL3 signaling in the brain specifically improves feeding behaviors without sparing lean or fat mass wasting during cancer cachexia." (PMID 36078078, 2022). "Herein, we summarize the cellular and molecular mechanisms of CNS dysfunction during cancer cachexia with a focus on inflammatory, autonomic and neuroendocrine processes and end with a discussion of recently identified CNS mediators of cachexia, including GDF15, LCN2 and INSL3." (PMID 34439145, 2021).